PADI3 (peptidyl arginine deiminase 3)
Description:
Catalyzes the deimination of arginine residues of proteins.
Synonyms: PAD3; PDI3; UHS1
Tractability: Small molecule: a structure with a bound ligand is known; a high-quality ligand is known; it belongs to a druggable protein family. PROTAC: ubiquitination databases record sites on it; a small molecule that binds it is known.
Target class: Enzyme; Hydrolase
Chemical probes: ML325
Gene: Protein-coding gene on chromosome 1 (17,249,098 to 17,284,233, forward strand). Ensembl gene ENSG00000142619.
Subcellular location: Cytoplasm
Subcellular location (Human Protein Atlas): Cytosol; Vesicles; Nucleoplasm
Pathways (Reactome):
Chromatin organization: Chromatin modifying enzymes
Gene Ontology:
Molecular function: identical protein binding; protein binding; protein-arginine deiminase activity; calcium ion binding
Cellular component: cytoplasm; cytosol; nucleus
Genetic constraint (gnomAD): Loss-of-function variants: 48 observed, 67.81 expected, observed/expected ratio (o/e) 0.71, 90% interval 0.56 to 0.9. The upper end of that interval is the gene's LOEUF score, 0.9, which puts it in group 3 of 6, group 1 being the genes least tolerant of losing a copy. Missense variants: 815 observed, 905.27 expected, observed/expected ratio (o/e) 0.9, 90% interval 0.85 to 0.95. Synonymous variants: 361 observed, 364.5 expected, observed/expected ratio (o/e) 0.99, 90% interval 0.91 to 1.08.
Homologues: Orthologues: chimpanzee PADI3 (99% identical), macaque PADI3 (97% identical), pig PADI3 (89% identical), guinea pig PADI3 (88% identical), rat Padi3 (88% identical), mouse Padi3 (87% identical), rabbit PADI3 (87% identical), zebrafish padi2 (46% identical). Paralogues in human: PADI1 (58% identical), PADI4 (56% identical), PADI2 (51% identical), PADI6 (45% identical).
Diseases named in the same sentence as PADI3 in open-access papers:
PADI3 is named in the same sentence as 52 diseases in open-access papers, as found by Europe PMC text mining. Sharing a sentence is not in itself a finding about the gene and the disease. The quoted sentences say what the papers report.
central centrifugal cicatricial alopecia (7 papers, 2020 to 2026). "This notion is further supported by a damaging mutation in PADI3 being associated with uncombable hair syndrome, central centrifugal cicatricial alopecia, and active EoE." (PMID 35472002, 2022). "As previously discussed, human PADI3 mutations are associated with Central centrifugal cicatricial alopecia (CCCA), a scarring alopecia developing in scalp regions exposed to repetitive mechanical stress and as a consequence, inflammation." (PMID 34966743, 2021). "In 2019, distinct heterozygous mutations also affecting the PADI3 gene were described as associated with another disease affecting the hair, namely the central centrifugal cicatricial alopecia (CCCA)." (PMID 33228136, 2020). "Human PADI3 mutations are linked to uncombable hair syndrome, manifesting as frizzy and fair hair resistant to combing flat, and Central centrifugal cicatricial alopecia (CCCA), a type of scarring alopecia found predominantly in women of African ancestry." (PMID 34966743, 2021). "Genetic studies have linked central centrifugal cicatricial alopecia (CCCA) and frontal fibrosing alopecia (FFA) to specific gene mutations, including PADI3 mutations on chromosome 1 and ERAP1/MHC class I variants on chromosome 5, respecitvely." (PMID 41362859, 2026). "Moreover, PADI3 is involved in hair shaft formation, and its loss causes morphological changes in hair, leading to the development of uncombable hair syndrome (UHS) and central centrifugal cicatricial alopecia (CCCA)." (PMID 37020554, 2023).
uncombable hair syndrome (7 papers, 2017 to 2025). Uncombable hair syndrome (UHS), or pili trianguli et canaliculi, is a rare scalp hair shaft dysplasia. "Human PADI3 mutations, affecting both PADI3 folding and enzymatic activity, are linked to uncombable hair syndrome, manifesting as frizzy and fair hair resistant to combing flat, and central centrifugal cicatricial alopecia, a scarring alopecia found predominantly in women of African ancestry." (PMID 40938992, 2025). "The CBS and PADI3 genes are associated with homocystinuria (MIM# 236200) and uncombable hair syndrome (MIM# 191480) respectively." (PMID 38584274, 2024). "Other downregulated genes, namely PADI3 and TCHH are associated with uncombable hair syndrome in humans and S100A3 has been connected with an age-dependent damage of the hair cuticle." (PMID 30794648, 2019). "Uncombable hair syndrome is caused by the lack of crosslinking of intermediate filaments in the IRS and CCCA patients display reduced levels of both trichohyalin and S100A3, suggesting that reduced PADI3-mediated citrullination affects both target function and stability in the human hair shaft." (PMID 34966743, 2021).
breast carcinoma (5 papers, 2016 to 2023). "CHD4 silencing strongly stimulated PADI1 and PADI3 expression in MCF7 breast cancer cells and increased glycolysis." (PMID 33741961, 2021). "While the types of breast cancer were not delineated in the study, an association between dysregulated PADI3, upregulated MMP9, triple-negative inflammatory breast cancer (TNIBC), and triple-negative non-inflammatory breast cancer (TN-NIBC) has been documented in the literature." (PMID 37109551, 2023). "Also, the use of specific internal peptide standards resulted in lower LLOQs as the cutoff for signal decay was improved by the presence of the standards’ corresponding transitions; this was particularly obvious for the measurement of PADI3 in the breast cancer samples." (PMID 30897176, 2019). "In this way, the genes selected for ChIP analysis were: PADI3, a tumour suppressor in CRC, ZDHHC2, a suppressor of metastasis in hepatocellular carcinoma and RGS4, which inhibits the growth of human breast carcinoma cells." (PMID 33801071, 2021). "Further studies should demonstrate the type of breast cancer associated with CCCA, as triple-negative breast cancer is associated with dysregulated PADI3 and MMP9." (PMID 37109551, 2023).
colon cancer (5 papers, 2019 to 2024). "In addition, the overexpression of SIRT2 was significantly associated with an increase of AKT phosphorylation in PADI3-expressing HCT116 colon cancer cells." (PMID 36297603, 2022). "The PADI3 has anticancer effect through the arresting of cell cycle in colon cancer, and it regulates the glycolysis in multiple cancer cell types." (PMID 35922788, 2022). "Our previous study showed that PADI3 plays an antitumor role in colon cancer by suppressing cell proliferation and cell colony formation, but the molecular mechanism is still unclear." (PMID 31708688, 2019). "The overexpression of PADI3 can induce the inhibition of cell proliferation and colony formation in colon cancer cells." (PMID 31708688, 2019). "In our previous study, we found that PADI3, which belongs to the PADs family, can inhibit cell proliferation via inducing G1-phase arrest to play its antitumor role in colon cancer." (PMID 31708688, 2019). "The expression pattern of PADI3 and CKS1 are negatively correlation in clinical samples of colon cancer, further study indicates that PADI3 can significantly decrease Hsp90 and CKS1 expression, and Hsp90 is essential for PADI3 to downregulate CKS1expression in colon cancer cells." (PMID 31708688, 2019). "PADI3 promotes cell cycle arrest via Sirt2-AKT-p21 and functions as a tumor suppressor gene in colon cancer." (PMID 36358967, 2022). "We found that PADI3 is an effective inhibitor of Hsp90 and CKS1 for regulating the cell cycle in colon cancer cells and that Hsp90 is essential for PADI3 to downregulate the expression of CKS1." (PMID 31708688, 2019). "However, the regulatory mechanism of PADI3 and CKS1 in the tumorigenesis of colon cancer is still unclear and need to do further research." (PMID 31708688, 2019). "According to that, we speculate that PADI3 may play its anti-tumor role via affect Hsp90, CKS1, CDK1 and p27kip1 expression in colon cancer." (PMID 31708688, 2019). "In the present study, we found that the expression pattern of PADI3, CKS1 and Hsp90 are negative correlation in colon cancer tissues, and overexpression of PADI3 can partly reverse CKS1 induced cell proliferation and colony formation." (PMID 31708688, 2019).
alopecia (4 papers, 2020 to 2025). Hair loss usually from the scalp. "We highlight PADI3 as a mediator of hair shaft differentiation and display why mutations in PADI3 are linked to human alopecia." (PMID 34966743, 2021).
hair disorder (3 papers, 2017 to 2024). "These comprise variants within genes associated with various types of human cancer (MAD1L1), Joubert syndrome 23 (KIAA0586), hair disorders (PADI3), mannose-binding lectin deficiency (MBL2), and multiple sclerosis (IL4R)." (PMID 36404349, 2023).
rheumatoid arthritis (3 papers, 2012 to 2019). A chronic, systemic autoimmune disorder characterized by inflammation in the synovial membranes and articular surfaces. "It is known to be distributed in hair follicles and keratinocytes, and a recent report indicated that PADI3 was strongly stained in macrophages (CD68-positive cells) in rheumatoid nodules and synovial tissue." (PMID 31532791, 2019). "A total of 320 SNPs from the PADI locus (including PADI1, PADI2, PADI3, PADI4 and PADI6 genes) were genotyped in 1,238 RA cases and 1,571 control subjects from the Malaysian Epidemiological Investigation of Rheumatoid Arthritis (MyEIRA) case-control study." (PMID 23164236, 2012).
cervical carcinoma (2 papers, 2021 to 2022). A carcinoma arising from either the exocervical squamous epithelium or the endocervical glandular epithelium. "CHD4 silencing in SiHa cervical carcinoma cells strongly diminished their colony forming capacity, potently increased PADI3 expression and stimulated glycolysis." (PMID 33741961, 2021).
clear cell renal carcinoma (2 papers, 2021 to 2024). A malignant epithelial neoplasm of the kidney characterized by the presence of lipid-containing clear cells within a vascular network. "Interrogation of the TCGA showed PADI1 and/or PADI3 expression in several solid tumours, bladder, pancreatic, cervical, head and neck and clear cell renal cancers with known hypoxic character." (PMID 33741961, 2021). "It has been reported that PADI3 is highly expressed in some solid tumors, such as bladder, pancreatic, cervical, head and neck, and clear-cell renal cancers, in which increased PADI3 enhances the citrullination of the glycolytic rate-limiting enzyme PKM2, leading to increased levels of glycolysis." (PMID 38474453, 2024).
HCMV infection (2 papers, 2021 to 2024). "Even though PADI2 and PADI4 are also marginally increased at the mRNA levels, their overexpression does not match the scale observed during HCMV infection of HFFs, where PADI3 expression remains basically unchanged." (PMID 39201398, 2024).
androgenetic alopecia (1 paper, 2020). "We found evidence to confirm the contributions of PADI3 to human variation in hair traits and suggest a novel potential candidate gene within known loci for androgenetic alopecia." (PMID 33167971, 2020).
autoimmune disorders (1 paper, 2016). "Further studies are also needed to more deeply investigate, in RA as well as in other autoimmune disorders where NETosis is involved, the role of PADI3/PADI4 SNPs in affecting enzyme levels and/or activity and possibly histone deimination and NET formation." (PMID 27255888, 2016).
COVID-19 (1 paper, 2020). A disease caused by infection with severe acute respiratory syndrome coronavirus 2. "PADI3 was found to be overall elevated in the marrow, the kidney and the lung of one COVID-19 case only." (PMID 32629995, 2020).
cutaneous melanoma (1 paper, 2021). A primary melanoma arising from atypical melanocytes in the skin. "Analyses of TCGA human tumour datasets showed strongly positively correlated co-expression of PADI1 and PADI3 in multiple tumour types such as cutaneous melanoma, uveal melanoma, bladder, lung and head and neck, with PADI1 often being the gene showing strongest correlation with PADI3." (PMID 33741961, 2021).
diabetic retinopathy (1 paper, 2018). "This region spans genes with plausible roles in the development of diabetic retinopathy, (e.g. PADI1, PADI2, PADI3, and PADI4, as well as genes known to be involved in kidney function (CLCNKA and CLCNKB)." (PMID 29444168, 2018).
endometrial cancer (1 paper, 2024). Primary or metastatic malignant neoplasm involving the endometrium (mucous membrane that lines the endometrial cavity). "Peptidyl arginine deiminase 3 (PADI3), as the candidate target gene of AT-II, was highly expressed in the endometrial cancer tissues and associated with a poor prognosis according to bioinformatics analysis." (PMID 38474453, 2024). "Then, we analyzed how PADI3 expression was upregulated in patients with endometrial cancer, and that high expression of PADI3 was associated with poor prognosis, suggesting that PADI3 may be involved in regulating endometrial cancer progression." (PMID 38474453, 2024). "PADI3 knockdown inhibited proliferation and glycolysis in endometrial cancer cells and induced cell apoptosis." (PMID 38474453, 2024). "From these data, we verified that PADI3 played an important role in endometrial cancer tumorigenesis, serving as a novel target for endometrial cancer therapy." (PMID 38474453, 2024). "The expression level of PADI3 was negatively correlated with overall survival, disease-specific survival, and progress-free interval of patients with endometrial cancer." (PMID 38474453, 2024). "PADI3 siRNA was transiently transfected into RL95-2 and AN3CA cells to identify the biological roles of PADI3 in endometrial cancer." (PMID 38474453, 2024). "However, no previous studies have experimentally investigated the potential roles of PADI3 in endometrial cancer." (PMID 38474453, 2024). "Furthermore, AT-II negatively regulated the expression of PADI3, and PADI3 overexpression reversed the effects of AT-II on endometrial cancer cells." (PMID 38474453, 2024). "To confirm this hypothesis, we transfected endometrial cancer cells with si-PADI3 and found that PADI3 knockdown suppressed cell proliferation and glycolysis, and induced apoptosis." (PMID 38474453, 2024). "As a candidate target, we evaluated whether PADI3 played an important role in the progression of endometrial cancer and had meaningful clinical value." (PMID 38474453, 2024). "Western blot and real-time PCR results were consistent with this result, highlighting that PADI3 may serve as an oncogene in endometrial cancer and in response to the anti-cancer activity of AT-II." (PMID 38474453, 2024). "The results showed that PADI3 was highly expressed in endometrial cancer tissues." (PMID 38474453, 2024). "In our study, we found that AT-II inhibited glycolysis and induced cell apoptosis by blocking the PADI3-ERK signaling pathway, thereby suppressing endometrial cancer cell growth." (PMID 38474453, 2024). "The data from the TCGA database were visualized using the Xiantao Academic online tool and the results showed that PADI3 mRNA was highly expressed in cancer tissues between paired or non-paired normal and endometrial cancer tissues." (PMID 38474453, 2024). "Nevertheless, the roles of PADI3 in endometrial cancer have not been previously explored." (PMID 38474453, 2024).
lung adenocarcinoma (1 paper, 2021). A carcinoma that arises from the lung and is characterized by the presence of malignant glandular epithelial cells. "In pancreatic adenocarcinoma, ccRCC, and lung adenocarcinoma, PADI1 and PADI3 expression was positively correlated with the hypoxic signature of the different patient samples." (PMID 33741961, 2021).
melanoma (1 paper, 2021). A malignant, usually aggressive tumor composed of atypical, neoplastic melanocytes. "In contrast, expression of PADI1 and PADI3 was strongly induced in all tested melanoma lines." (PMID 33741961, 2021). "To test this idea, we grew 501Mel melanoma cells in hypoxic conditions where PADI1 and PADI3 expression was induced concomitantly with the hypoxia responsive gene VEGF." (PMID 33741961, 2021). "Analyses of the Cancer Cell Line Encyclopaedia (CCLE) showed a strong correlation of PADI1 and PADI3 expression indicating their co-regulation was not restricted to melanoma cells." (PMID 33741961, 2021).
multiple myeloma (1 paper, 2020). "In marrow, PADI2 and PADI3 were elevated in some SARS-CoV-2 biopsies, and interestingly PADI2 was found to be elevated in marrow mesenchymal stem cells, which upregulates IL-6 via histone H3 deimination in multiple myeloma, contributing to chemo-resistance." (PMID 32629995, 2020).
psoriasis (1 paper, 2022). An autoimmune condition characterized by red, well-delineated plaques with silvery scales that are usually on the extensor surfaces and scalp. "Genetic Polymorphisms of PADI3 are associated with skin disorders such as uncombable hair syndrome and certain forms of alopecia, while reduced levels of keratin K1 citrullination are thought to compromise skin structure and are associated with psoriasis and atopic dermatitis." (PMID 35706669, 2022).
viral infection (1 paper, 2023). "Having established that PAD3 was the most significantly impacted PAD family member by HSV-1 infection, we sought to determine the mechanism underlying PADI3 transcriptional upregulation in response to viral infection." (PMID 38055760, 2023).
infection (24 papers, 2010 to 2024). The state of being infected such as from the introduction of a foreign agent such as serum, vaccine, antigenic substance or organism. "HSV-1 infection led to a robust induction of the luciferase activity driven by PADI3 promoter (~6 fold) and upregulated viral ICP27 expression at 24 hpi, indicating once more than early stages of infection are critical for the transcriptional activation of PADI3 gene." (PMID 38055760, 2023).